CDC42 (cell division cycle 42)
Diseases named in the same sentence as CDC42 in open-access papers (continued):
Sharing a sentence is not in itself a finding about the gene and the disease.
hepatocellular carcinoma (32 papers, 2010 to 2025). A malignant tumor that arises from hepatocytes. "However, deletion of Cdc42 has also been linked to tumour formation in some cancer types, with one study demonstrating that deletion of Cdc42 in hepatocytes induced spontaneous hepatocellular carcinoma formation in vivo." (PMID 34196668, 2021). "The overexpression of CDC42 promotes hepatocellular carcinoma proliferation, metastasis, and tumor growth in vivo." (PMID 36792578, 2023). "For example, Cdc42 is overexpressed and activated in hepatocellular carcinoma, correlating with reduced E-cadherin expression and an enhanced EMT phenotype." (PMID 36077689, 2022). "In hepatocellular carcinoma, it has been reported that H19 positively regulates CDC42 via sponging miR-15b." (PMID 34168124, 2021). "ARHGEF9 has been shown to play a role in tumor cell migration, invasion and metastasis by linking oncogene CHD1L and Cdc42 pathway in hepatocellular carcinoma (HCC)." (PMID 32503434, 2020). "Hepatocyte-specific Cdc42 knockout mice showed hepatomegaly, slow growth, and chronic jaundice and frequently developed hepatocellular carcinomas at 8 months of age." (PMID 29596304, 2018). "The results of the CTPAC online tool implied that CDC42 protein was enriched in clear cell renal cell carcinoma (ccRCC, p = 1.7e-08), hepatocellular carcinoma (HCC, p = 1.0e-05), head and neck cancer (HNSC, 5.3e-18), and endometrioid cancer (UCEC, p = 1.5e-09) compared to normal tissues." (PMID 37476838, 2023). "A previous study demonstrated that CHD1L upregulates the expression of ARHGEF9, which subsequently activates Cdc42, causing filopodia formation, epithelial-mesenchymal transition (EMT), and finally promotes hepatocellular carcinoma cell invasion and metastasis." (PMID 32922205, 2020). "On the contrary, gene knockout studies suggest that CDC42 might also function as a tumor suppressor because targeted knockout of the CDC42 gene in hepatocytes or blood stem/progenitor cells resulted in the development of hepatocellular carcinoma or myeloproliferative disease in mice." (PMID 38386112, 2024). "But Cdc42 may act as an anti-cancer gene in hepatocellular carcinoma." (PMID 29596304, 2018). "report that the immuno‐effect of the CD42 inhibitor outweighs any tumor cell‐intrinsic effect, it has also been reported that a low level CDC42 in the serum can predict the clinical response to ICI in patients with advanced hepatocellular carcinoma (HCC) and advanced cervical cancer." (PMID 39791593, 2025). "In hepatocellular carcinoma cells, miR151 down-regulated the Rho GDP dissociation inhibitor α (RhoGDIA) coding transcript, and as a result RAC1, CDC42, and RHO were activated and cell migration was promoted." (PMID 37582765, 2023). "However, gene knockout studies suggested that CDC42 might function as a tumor suppressor, because targeted ablation of CDC42 gene in the hepatocytes or blood stem/progenitor cells resulted in the development of hepatocellular carcinoma or myeloproliferative disease in mice." (PMID 26336992, 2015). "For example, in hepatocellular carcinoma cells, ARHGEF37 can activate CDC42 by interacting with it." (PMID 36870986, 2023). "Other MAPK members have been upregulated by HMGB1 including cell division control protein 42 homolog (Cdc42)/Ras-related C3 botulinum toxin substrate 1 (Rac1)/mitogen-activated protein kinase kinase 6 (MKK6)/p38 that led to the proliferation of human rhabdomyosarcoma and hepatocellular carcinoma." (PMID 32443845, 2020). "In hepatocellular carcinoma CTHRC1 promotes cell adhesion through activation of integrin β1 and phosphorylation of focal adhesion kinase (FAK), while the activation of RhoA, but not Rac1 or Cdc42 plays a crucial role." (PMID 27430622, 2016).
diabetes (26 papers, 2009 to 2025). "Recent studies have identified a crucial role for CDC42 in the progression of diabetes and diabetes-associated diseases, such as insulin resistance and diabetic nephropathy." (PMID 35537778, 2022). "We showed that Cdc42 functions as a regulator of diabetes-associated tissue injury, manifesting as an insulin secretion disorder with podocyte apoptosis." (PMID 36034435, 2022). "Cell division cycle 42 (Cdc42), a small GTPase of the Rho family, can regulate insulin secretion and diabetes-associated diseases such as diabetic nephropathy (DN) and diabetic foot." (PMID 34447414, 2021). "In this review, we summarized the regulation of Cdc42 in insulin secretion and diabetes-associated diseases." (PMID 30621321, 2019). "Through the current review, we hope to cast light on the mechanism of Cdc42 in diabetes and associated diseases and provide new ideas for clinical diagnosis, treatment, and prevention." (PMID 30621321, 2019). "In the current review, we summarized the role of Cdc42 in insulin secretion, as well as the relationship between Cdc42 and diabetes-associated diseases, including IR, DN, and cancer." (PMID 30621321, 2019). "Similarly, significant differences in Rho family GTPase signalling, namely, the Rac3 and Cdc42 pathways, which regulate cytoskeletal organisation and membrane trafficking and have been proposed to be linked to diabetes, were among the top ten pathways scored." (PMID 23841104, 2013). "Especially, CDC42 was reported as a regulator for not only diabetes, but also insulin secretion and development." (PMID 41000275, 2025). "Literature supporting a role for cDC42 and therefore Pak1 signaling as a critical component of insulin secretion and diseases related to diabetes has been summarized in extensive reviews." (PMID 40065530, 2025). "Antigen-activated lymphocytes showed that diabetes impaired the mRNA expression of the protein kinase B (Akt1), Cdc42, and the co-stimulatory molecule, CD28, which are important for cell survival, actin polymerization and T cell activation, respectively." (PMID 25009576, 2014). "Importantly, dysregulation of Cdc42 in diabetes progression participates in insulin resistance, diabetic neuropathy, and metastasis of tumors under hyperglycemic conditions." (PMID 40065530, 2025). "Disorder of CDC42, can prevent healthy insulin secretion and promote diabetes." (PMID 39160196, 2024). "The results imply that inhibiting Cdc42 in hyperglycemia may be a potential therapy for promoting tissue regeneration in diabetes, and so should help for various diabetic complications, e.g. the diabetic foot or stroke." (PMID 38343879, 2024). "VAMP2 and Cdc42 localize together at the plasma membrane and on insulin secretory granules in β-cells and play vital functions in insulin secretion and development of diabetes." (PMID 34394002, 2021). "Cdc42 involves in the pathomechanism of diabetes, here we try to figure out whether Cdc42 relates to cancers under hyperglycemic condition." (PMID 30621321, 2019). "Disorder of Cdc42 will impair normal insulin secretion and contribute to diabetes." (PMID 30621321, 2019). "However, the role of Cdc42 in cancer-related to diabetes or high glucose condition is still partly unclear and remains to be discovered with further study." (PMID 30621321, 2019). "Many studies have demonstrated that β-catenin can be regulated effectively by Cdc42, and we hypothesized that miR-29a/Cdc42/β-catenin is a potential signaling cascade involved in diabetes progression." (PMID 31662747, 2019). "Organized researches indicate that Cdc42 is a crucial member during the progression of diabetes, and Cdc42 not only participates in the process of insulin synthesis but also regulates the insulin granule mobilization and cell membrane exocytosis via activating a series of downstream factors." (PMID 30621321, 2019).
diabetes (continued). "Not surprisingly, given the prominent role of Cdc42 in so many aspects of cell biology, aberrant activation of Cdc42 (or dysfunction of Cdc42 GEFs) results in pathogenesis, including tumorigenesis and tumor progression, cardiovascular diseases, diabetes, and neuronal degenerative diseases." (PMID 22589722, 2012). "CDC42 is a gene participating in the rearrangement of actin cytoskeleton, membrane trafficking and cell-cycle progression, and it appears to be involved in cardiovascular diseases, diabetes and neuronal degenerative diseases." (PMID 20015360, 2009). "Therefore, we suggested that the inhibition of Cdc42 might be a promising strategy to facilitate various tissue regeneration for diabetes patients." (PMID 38343879, 2024). "miR-29a/Cdc42/β-catenin may be involved in diabetes progression." (PMID 31662747, 2019). "Thus, we hypothesized that miR-29a can affect the expression of Cdc42 during diabetes progression." (PMID 31662747, 2019). "However, further animal experiments and studies of clinical samples from patients are needed to validate the function of miR-29a/Cdc42/β-catenin, and whether other miRNAs and downstream molecules play crucial roles in diabetes progression also requires further studies." (PMID 31662747, 2019). "mRNA expression of the activated lymphocytes showed that diabetes impaired the Akt1 (234 ± 9.5), CD28 (229 ± 14) and Cdc42 (33 ± 6.5) signaling compared to those of the control group [Akt1 (252 ± 12), CD28 (235 ± 10), Cdc42 (45 ± 5.0)]." (PMID 25009576, 2014). "However, additional studies are needed to confirm whether CDC42 affects the pathogenesis of AMI by mediating insulin resistance, diabetes, obesity and other processes." (PMID 35537778, 2022). "Namely, downregulation of GluN1 in podocytes in culture and in glomeruli led to a marked increase of Cdc42-GTP levels, with no changes in levels of RhoA and Rac1, after in vitro high-glucose exposure or in vivo induction of diabetes, supporting a direct inhibitory role of NMDARs on Cdc42 activation." (PMID 32679780, 2020). "Interestingly, our new analysis procedure subsequently identified CDC42 and PTBP1 as being equally targeted by both up- and down-regulated miRNAs; thus, CDC42 and PTBP1 should not be altered in vivo by diabetes (as we demonstrated by western blotting prior to developing our ranking metric)." (PMID 20353613, 2010).
neuroblastoma (23 papers, 2006 to 2023). Neuroblastoma (NB) is the most common solid, extracranial childhood tumor. "In the neuroblastoma cell line, it was demonstrated that Rab8a activity promotes Cdc42 activation through Tuba." (PMID 36779014, 2023). "Bioinformatics analysis using starBase showed, among 8 potential targets which were expressed in neuroblastoma, that CDC42 and BCL2 mRNA levels were up-regulated most in SK-N-SH cells." (PMID 31889909, 2019). "Surprisingly, as opposed to its well reported repulsive role, overexpression of Unc5a in N1E-115 neuroblastoma cells has been shown to induce neurite outgrowth by increasing Rac1 and Cdc42 activity." (PMID 30934641, 2019). "Consistently, neuroblastomas with N-myc amplification display deletions of the short arm of chromosome 1 containing the Cdc42 gene in 90–95% of cases, and one copy of Cdc42 is consistently lost in this type of cancer." (PMID 28871124, 2017). "This is supported by the finding that CDC42 expression was increased through over-expression of AhR in mouse Neuro2a neuroblastoma cells." (PMID 28860601, 2017). "In N1E-115 neuroblastoma cell line, Cdc42 promotes the formation of filopodia and lamellipodia, whereas RhoA causes GC collapse and neurite retraction." (PMID 26379503, 2015). "Products of the NME1 and NME2 genes have been suggested to be the downstream of the c-myc regulatory pathway and involved in the down-regulation of cdc42 function in neuroblastoma." (PMID 25700270, 2015). "In this study, by using hsa-miR-608 mimic and inhibitor, we confirmed that hsa-miR-608 could target CDC42 and down-regulate its expression in SK-N-SH neuroblastoma cells." (PMID 28860601, 2017). "In addition, silencing of Cdc42 has been shown to inhibit cell proliferation in neuroblastoma cells." (PMID 27486972, 2016). "Furthermore, a reduction of syncrip induced evident morphological changes in rat cortical neurons and mouse neuroblastoma cells by regulating actin dynamics via the Cdc42/N-WASP/Arp2/3-pathway." (PMID 23758873, 2013). "Additionally, in a study using mouse hippocampal neurons and N1E-115 neuroblastoma cell line, it was demonstrated that Tuba, a Cdc42 GEF, was required for neuronal polarization, as shRNA knockdown of Tuba increased the number of unpolarized neurons as well as decreased axonal length." (PMID 36779014, 2023). "Additionally, CDC42 knockdown induced cell cycle arrest and apoptosis in neuroblastoma cells." (PMID 30717410, 2019). "Therefore, we hypothesize that transcriptional up-regulation via AhR pathway might participate the dioxin-mediated CDC42 induction in the present human neuroblastoma cells." (PMID 28860601, 2017). "By targeting BCL2 and cell division cycle 42 (CDC42), miR-149-5p promotes apoptotic cell death, represses cell proliferation, and alleviates doxorubicin resistance in neuroblastomas." (PMID 35055115, 2022). "Knockdown or inhibition of CDC42 in GBM and neuroblastoma cells decreases proliferation and invasion, while increasing chemosensitivity." (PMID 33466745, 2021). "Work in fibroblasts, rat commissural neurons, and N1E-115 neuroblastoma cells showed that netrin-1/DCC signaling increases Rac1 and Cdc42 activities, while decreasing RhoA activity." (PMID 30934641, 2019). "We found that Cdc42 and RhoA were activated at the leading edge of NG108-15 neuroblastoma cells during spontaneous cycles of protrusion and retraction, respectively." (PMID 26379503, 2015). "Neuroblastoma cells were incubated with JNK inhibitor (SP600125; 20 μM) with metformin (10 mM) in presence of Rac1 inhibitor (NSC23766; 25 μM) or Cdc42 inhibitor (ML141; 10 μM), and cell viability was measured." (PMID 25365944, 2014). "We showed that paxillin phosphorylation, acting through the Rac1/Cdc42/cJNK signaling cascade, is activated following neurite extension in mouse N1E115 neuroblastoma cells." (PMID 23626709, 2013).
neuroblastoma (continued). "p250GAP is a large, brain-enriched GAP, which hydrolyses RhoA-GTP and Cdc42-GTP and was found to regulate neurite growth in a neuroblastoma and PC12 cell line." (PMID 23226367, 2012). "Indeed, TENM4 KO neuroblastoma cells of mouse origin display decreased neurite length and ability to generate filopodia-like protrusions through FAK, Cdc42 and Rac1, whereas TENM4 overexpression in neuroblastoma cells promotes protrusion formation." (PMID 33652578, 2021). "ML141 was recently used as a potent Cdc42 inhibitor in cancer stem cells to downregulate epidermal growth factor receptor (EGFR) and redox/Fyn/c-Cbl signaling pathways, and to regulate apoptosis in neuroblastoma cells." (PMID 29921325, 2018). "By expressing constitutively active or dominant negative forms of Rho GTPases, and by using specific inhibitors of Rac1, Cdc42, and JNK, we further confirmed the role of impairments in Rho GTPase signaling in mediating metformin effects on the survival of neuroblastoma cells." (PMID 25365944, 2014). "Thus, the JNK phosphorylation of paxillin, possibly after Rac1/Cdc42 signaling cascade stimulation, plays a critical role in neurite extension in mouse N1E115 neuroblastoma cells." (PMID 23626709, 2013). "For some genes only circumstantial evidence for a role in neuroblastoma is present (WSB1, CDC42, PLAGL1, PRAME and TGFBR3); that we identified these genes in the present study warrants further investigations into their possible role in neuroblastoma development." (PMID 16989664, 2006). "In this paper, we examine the role of RhoA and Cdc42 in NG108-15 neuroblastoma cells and we show that they are both involved in Sema3A morphological changes with specific spatio-temporal dynamics; we also show that Cdc42 (but not RhoA) exhibits a complex wave behavior." (PMID 26379503, 2015). "However, we did not observe altered intracellular distribution of PAK5 in the degenerating retina (data not shown), suggesting that a CDC42-dependent PAK5 translocation mechanism similar to neuroblastoma may not be involved in photoreceptor apoptosis." (PMID 22128240, 2011).
endometriosis (20 papers, 2017 to 2026). The growth of functional endometrial tissue in anatomic sites outside the uterine body. "Such approaches identified that variants regulating the expression of genes involved in cell adhesion and proliferation, LINC00339, VEZT, FGD6, and CDC42, in endometrium and blood, also increase risk of endometriosis." (PMID 36746607, 2023). "Endometriosis risk alleles in the chr1 region have been associated with increased expression of CDC42, and active TSSs in ESCs were also located in the CDC42 endometriosis risk locus." (PMID 37443771, 2023). "This indicates another possible mechanism for lncRNA regulation, whereby dysregulation of CDC42 due to the risk of an SNP affecting enhancer competition with the LINC00339 promoter leads to predisposition to endometriosis." (PMID 34768856, 2021). "Consistent with the importance of Wnt regulation, LINC00339 and its linked gene CDC42 are involved in both endometriosis and bone metabolism, two Wnt-regulated biological processes." (PMID 33092630, 2020). "By extending the genomic window around the consensus clusters by 2 kb to account for the promoter region, consensus clusters were found to overlap 11 endometriosis-associated SNPs across 6 genomic regions, including gene regions near FGD6, ARL14EP and CDC42." (PMID 37443771, 2023). "GnRH-activated CDC42 regulates FSH and LH in response to pulsatile GnRH, there is also evidence that CDC42 regulates ovarian reserve, follicle activation and granulosa cell function, suggesting that altered CDC42 regulation may be implicated in fertility issues associated with endometriosis." (PMID 37443771, 2023). "Expression of several of these genes (LINC00339, CDC42, GDAP1, FGD6, SRP14) has been associated with risk of endometriosis previously." (PMID 37587191, 2023). "Genes shared between endometriosis, uterine fibroids, ovarian and endometrial cancer, asthma and migraine (CDC42, WNT4, SMAD3, SKAP1) were enriched in cell adhesion pathways." (PMID 37159502, 2023). "Genes in the 1p36.12 locus (CDC42, WNT4, and LINC00339) have been associated with endometriosis, uterine fibroids, ovarian and endometrial cancers, and asthma." (PMID 37159502, 2023). "The rs3820282 SNP located within a WNT4 intron on chromosome 1p36.12 is associated with endometriosis and appears to affect an enhancer–promoter interaction resulting in the downregulation of LINC00339 and upregulation of CDC42." (PMID 34768856, 2021). "Our UL GWAS meta-analysis indicates that genes previously associated with endometriosis and involved in hormone-signaling pathways are also associated with UL (WNT4/CDC42, GREB1, ESR1, and FSHB)." (PMID 31649266, 2019). "The SMR analysis identified two potential causal genes, CDC42 (rs2268177; PSMR=1.07 × 10−12) and VEZT (rs14121; PSMR=3.41 × 10−6), underlying endometriosis loci at 1p36.12 and 12q22, respectively." (PMID 28537267, 2017). "Functional studies investigating the interaction between genetic variants on chr1p36.12 and nearby genes suggested that endometriosis risk variants interact with the promoters of LINC00339, CDC42 and WNT4 and the risk allele is associated with increased expression of CDC42 in blood cells." (PMID 36746607, 2023). "Though these considerations support WNT4 as a candidate predisposition gene at this locus, the near-by CDC42 has been shown to play a role in uterine pathology, in particular endometriosis, and should not be overlooked in further work." (PMID 30226466, 2018). "Signals for mQTLs significantly associated with endometriosis on chromosome 1p36.12, including two potentially endometrial-specific mQTLs, were located in regulatory regions and associated with the expression of known genes of interest LINC00339, CDC42, and WNT410,24,41,42." (PMID 37587191, 2023).